COL9A2 (collagen type IX alpha 2 chain)
Diseases named in the same sentence as COL9A2 in open-access papers:
COL9A2 is named in the same sentence as 56 diseases in open-access papers, as found by Europe PMC text mining. Sharing a sentence is not in itself a finding about the gene and the disease. The quoted sentences say what the papers report.
Stickler syndrome (18 papers, 2013 to 2024). "Specifically, HM was identified in six children with retinal dystrophies (RPGR; N = 2, CACNA1F; N = 2, RP2, NDP) and one child each of corneal dystrophy (ZEB1) and Stickler syndrome (causative variant in the COL9A2 gene)." (PMID 39495751, 2024). "The differential diagnosis included MED and Stickler syndrome, both of which are associated with COL9A2 mutations." (PMID 38989334, 2024). "Mutations in Col1a2 are associated with osteogenesis imperfecta, while mutations in Col2a1 and Col9a2 are linked to Stickler syndrome." (PMID 38413848, 2024). "In LER (CD−M2), Ush1c, Otogl, Gjb2, and Eps8 were associated with NSHL; Ush1c and Clrn1 with Usher syndrome, Six1 with branchiootorenal syndrome; Gjb2 with skin phenotype and HL; Gata3 with hypoparathyroidism, sensorineural hearing loss, and renal dysplasia; and Col9a2 with Stickler syndrome." (PMID 39684410, 2024). "The COL9A2 gene, however, has been implicated in two main clinical syndromes: MED and Stickler syndrome." (PMID 38989334, 2024). "By contrast, Stickler syndrome has the most collagens (six) linked to this syndrome (COL2A1, COL9A1, COL9A2, COL9A3, COL11A1, and COL11A2), followed by Ullrich congenital muscular dystrophy, with four collagens associated (COL6A1, COL6A2, COL6A3, and COL12A1)." (PMID 37189830, 2023). "Homozygous Type IX collagen variants (COL9A1, COL9A2, and COL9A3) causing recessive Stickler syndrome." (PMID 35198553, 2022). "The known causative genes of Stickler syndrome are COL2A1, COL11A1, COL11A2, COL9A1, COL9A2, and COL9A3." (PMID 34680973, 2021). "Mutations in COL9A1, COL9A2 and COL9A3 cause multiple epiphyseal dysplasia (MED), an autosomal dominant chondrodysplasia, Stickler syndrome." (PMID 34572492, 2021). "Stickler syndrome caused by COL2A1, COL11A1, and COL11A2 genes has a dominant inheritance, whereas COL9A1, COL9A2, and COL9A3 genes show a recessive inheritance." (PMID 34680973, 2021). "Since Stickler syndrome caused by COL9A1, COL9A2, and COL9A3 variants is very rare, most of the patients with Stickler syndrome are STL1 or STL2 patients if they have ocular abnormalities." (PMID 34680973, 2021). "To date, mutations in seven genes (COL2A1, COL11A1, COL11A2, COL9A1, COL9A2, COL9A3, and LOXL3) have been reported to cause Stickler syndrome." (PMID 32756486, 2020). "More rare than the AD forms, biallelic pathogenic variants in COL9A1, COL9A2, and COL9A3 have been reported to cause recessive forms of Stickler Syndrome (Stickler Syndromes 4-6 [STL4-6])." (PMID 32867104, 2020). "To date, multiple mutations in the collagen-encoding genes COL2A1, COL11A1, COL11A2, COL9A1, COL9A2, and COL9A3 have been associated with six genetically distinct types of Stickler syndrome." (PMID 28335520, 2017). "In humans, Stickler syndrome caused by mutations of COL2A1, COL11A1, COL11A2, COL9A1 and COL9A2, is one of the most common connective tissue disorders characterized by ocular, skeletal, orofacial and auditory defects." (PMID 26307084, 2015). "Stickler syndrome is commonly caused by mutations in different collagen genes, namely COL2A1, COL11A1 and COL11A2 (autosomal dominant inheritance) and COL9A1 and COL9A2 (autosomal recessive inheritance)." (PMID 26307084, 2015). "Since 2006, mutations in the collagen type IX alpha 1 (COL9A1) and collagen type IX alpha 2 (COL9A2) genes, encoding for type IX collagen, have been reported as causal for an autosomal recessive form of Stickler syndrome." (PMID 23592912, 2013). "In this case, the presence of a specific COL9A2 gene mutation raised the possibility of an association with Stickler syndrome, although the patient's presentation did not include all typical features of the syndrome." (PMID 38989334, 2024).
Stickler syndrome (continued). "These systemic syndromes can be caused by a series of genes, including NYX, CACNA1F, GRM6, and LRIT3, responsible for congenital stationary night blindness (CSNB); COL2A1, COL11A1, COL9A1, and COL9A2, responsible for Stickler syndrome; and FBN1, responsible for Marfan syndrome." (PMID 36980859, 2023). "Indeed, mutations in COL2A1, COL11A1, COL11A2, COL9A1, COL9A2, and COL9A3 have been associated with Stickler syndrome and early-onset OA." (PMID 28335520, 2017). "Similarly, mutations in the collagen-α chain genes, COL2A1, COL9A2, COL11A1, and COL11A2, have been associated with different forms of Stickler syndrome (OMIM#108300, #614284, #604841, and #184840, respectively), a clinically variable condition that includes cleft palate." (PMID 28106045, 2017). "Type 4, 5 and 6 Stickler syndromes (STL4, STL5 and STL6) have been attributed to homozygous or compound heterozygous mutations in the type IX collagen genes COL9A1, COL9A2 and COL9A3, respectively." (PMID 36140739, 2022). "In this case, the presence of a COL9A2 gene mutation raised the possibility of an association with MED and Stickler syndrome, although the patient's presentation did not include all typical features of these syndromes." (PMID 38989334, 2024).
multiple epiphyseal dysplasia (7 papers, 2006 to 2025). Multiple epiphyseal dysplasias (MED/EDMs) are characterized by epiphyseal anomalies causing joint pain early in life, recurrent osteochondritis and early arthrosis. "In addition, the importance of CIX was highlighted when a form of multiple epiphyseal dysplasia, EDM2, was linked to the col9a2 gene." (PMID 16813664, 2006). "Multiple epiphyseal dysplasia (MED) may be caused by mutations of genes encoding collagen IX, namely COL9A1 (encoding α1 chain), COL9A2 (α2 chain), and COL9A3 (α3 chain), but such mutations are not the main cause of MED." (PMID 35883515, 2022). "The genes implicating BMD variation and multiple epiphyseal dysplasias (MED) like COL1A1, COL1A2, CO9A1, COL9A2 and COL9A3 were highly suggestive in humans." (PMID 19284518, 2009).
autosomal recessive Stickler syndrome (4 papers, 2012 to 2021). "A loss-of-function mutation in COL2A1 and COL9A2 identified as a causative locus in autosomal recessive Stickler syndrome characterized by orofacial and auditory abnormalities." (PMID 34639189, 2021). "A loss-of-function variant in COL9A2 has been associated to autosomal recessive Stickler syndrome, in which vitreoretinal degeneration is one of the symptoms together with other ocular, auditory, skeletal and orofacial abnormalities." (PMID 32150541, 2020). "A loss of function mutation in Col9a2 was identified as a causative locus in autosomal recessive Stickler syndrome, characterized by hearing loss and ocular, skeletal, and orofacial abnormalities." (PMID 25852475, 2015). "Autosomal recessive Stickler syndrome has been described in some families with mutations in COL9A1 (STL4) and COL9A2 (STL5) encoding type IX collagen." (PMID 23110709, 2012).
disc degeneration (3 papers, 2009 to 2021). "Earlier data also suggest that disc degeneration and the clinical outcome after sciatica may be associated with the large molecule collagen type IX alpha 2 (COL9A2)." (PMID 27964712, 2016). "COL9A2 was significantly (P < 0.05) associated with top line and rear leg and feet soundness traits in the pig and it was related to degenerative lumbar spinal stenosis and inter-vertebral disc disease in humans." (PMID 19284518, 2009). "Meta-analysis using a random effect model demonstrated an increased risk of disc degeneration in COL9A2 Trp2 carriers compared to non-carriers (OR = 1.43, 95% CI 0.99–2.06, I2 = 64.1%)." (PMID 34663366, 2021).
hearing loss (3 papers, 2020 to 2022). "The remaining gene variants in CEACAM16, COL11A1, COL9A2, DIAPH1, TCOF1 were tested for segregation with the hearing loss phenotype in the extended family." (PMID 35292975, 2022).
lumbar disc degeneration (3 papers, 2018 to 2024). "SNPs that result in tryptophan polymorphisms in collagen IX genes, such as Trp2 allele (p.Gln326Trp) in COL9A2 and Trp3 allele in COL9A3, have been linked to an increased risk of lumbar disc disease in different populations." (PMID 38166944, 2024). "An increasing number of studies have investigated associations between collagen IX alpha 2 chain (COL9A2) and collagen IX alpha 3 chain (COL9A3) gene polymorphisms and the risk of lumbar disc degeneration (LDD)." (PMID 29506578, 2018).
osteoarthritis (3 papers, 2012 to 2024). A noninflammatory degenerative joint disease occurring chiefly in older persons, characterized by degeneration of the articular cartilage, hypertrophy of bone at the margins and changes in the synovial membrane. "Studies have revealed that genes such as Mcf2l, Pthrp, Col2a1, and Col9a2, associated with osteoarthritis, are dynamically expressed during zebrafish development." (PMID 32824602, 2020). "A degenerative skeletal disease such as osteoarthritis has been investigated using for example Mcf2l, Gdf5, Col9a2, col11a2 zebrafish mutants." (PMID 32824602, 2020). "Mutations in COL9A2 and COL9A3 have previously been linked to human disk disease and studies in transgenic mice have further demonstrated that mutations in collagen IX can lead to disk degeneration but also degenerative joint disease." (PMID 23125846, 2012).
Arthritis (2 papers, 2018 to 2023). Inflammation of a joint. "This hypothesis was also enlightened further with upregulation of COL9A2, which shows increase in its expression in arthritis and TLR2, which will upregulate MMP increasing collagenolysis and aggrecanolysis." (PMID 29731966, 2018).
Epiphyseal dysplasia (2 papers, 2009 to 2021). "FIN35-3 also carried a de novo variant p.(Gly382Val) in COL9A2 implicated in AR Stickler syndrome and AD epiphyseal dysplasia." (PMID 33710394, 2021). "Additionally, mutations in COL9A2 cause epiphyseal dysplasia, yet there is not yet a targeted mouse model for this gene." (PMID 20046828, 2009).
osteochondritis dissecans (2 papers, 2010 to 2024). A rare bone disease characterized by an acquired idiopathic necrotic lesion of subchondral bone with the formation of a sequestrum, which may detach to form loose bodies in joints. "In this study we have identified COL9A2 mutations in two families with MED that also have osteochondritis dissecans and mild myopathy." (PMID 20358595, 2010). "Additional manifestations have been reported in MED, as Versteylen and colleagues (1998) described two COL9A2-MED families with prevalent osteochondritis dissecans (OCD)." (PMID 39596690, 2024). "Other complications have been reported, in particular osteochondritis dissecans (OCD), which has been described in two large COL9A2-related MED families associated with myopathy." (PMID 39596690, 2024).
osteogenesis imperfecta (2 papers, 2024 to 2025). Osteogenesis imperfecta (OI) comprises a heterogeneous group of genetic disorders characterized by increased bone fragility, low bone mass, and susceptibility to bone fractures with variable severity. "DNA sequencing panels for osteogenesis imperfecta and bone fragility as well as connective tissue disorders revealed a heterozygous c.1018G>A, p.Gly340Ser paternal COL9A2 variant of unknown significance (VUS)." (PMID 40062121, 2025). "DNA sequencing panels for osteogenesis imperfecta and bone fragility as well as connective tissue disorders revealed a heterozygous c.1018G>A, p.Gly340Ser paternal COL9A2 VUS." (PMID 40062121, 2025).
cardiac hypertrophy (1 paper, 2016). "Data also showed up-regulation of about 180 genes including Tgfb2, Ace, Atf3, Ctgf, Angpt14, Col9a2, Wisp2, Nppa, Nppb, and Actn1 that are linked to cardiac muscle contraction, cardiac hypertrophy, cardiac fibrosis and myocardial injury." (PMID 27548259, 2016).
chondrodysplasia (1 paper, 2022). "Besides, P.7 carries pathogenic variants in both COL2A1 and COL9A2 mutations resulting in a more severe skeletal deformity and short-trunk dwarfism, while the other two patients (P.16, P.17) in our study only carrying COL9A1/COL9A2 mutation had very mild symptoms, with only mild chondrodysplasia." (PMID 35250876, 2022).
chondrosarcoma (1 paper, 2025). A malignant cartilaginous matrix-producing mesenchymal neoplasm arising from the bone and soft tissue. "This included decreased COL9A2 transcripts upon expression of IDH1 R132Q versus WT, a type IX collagen often downregulated in high-grade versus low-grade chondrosarcomas." (PMID 40188944, 2025).
chordoma (1 paper, 2021). Chordomas are rare malignant tumors arising from embryonic remnants of the notochord in axial skeleton. "We observed col9a2 expression in regions of damage within the notochord, suggesting sheath cell migration towards the chordoma wounded area." (PMID 33579726, 2021).
clubfoot (1 paper, 2023). The most common congenital deformation of the foot, occurring in 1 of 1,000 live births. "Mutations in genes encoding the ECM proteins COL9A1, COL9A2, COL9A3, COMP and MATN3, as well as the transmembrane glycoprotein involved in matrix organization, SLC26A2, have been associated with clubfoot." (PMID 37964341, 2023).
deafness (1 paper, 2024). An inherited or acquired condition characterized by the complete loss of the ability to hear from one or both ears. "They found that numerous deafness-related genes (e.g. Col9a2, Lmx1a, and Sox10) were downregulated, and single-cell transcriptome data from Chd7KO/+ organoids also showed that some deafness-related genes (e.g. Six1, Ush1c, and Strc) were downregulated in HCs, implying that." (PMID 38015350, 2024).
diabetes (1 paper, 2021). "Differentially regulated genes not overlapping with ERCB data also reflected diabetes-associated changes, such as extracellular matrix (ANGPTL4, TNN, DPT, COL9A2) or gestational diabetes (LAT2, HP, CXCL10, CD86, CD68, REN, SLC2A3, VCAM1)." (PMID 33923831, 2021).
dwarfism (1 paper, 2019). "Autosomal recessive OSD caused by COL9A3 and COL9A2 mutations have previously been identified in the Labrador Retriever (dwarfism with retinal dysplasia 1—drd1) and Samoyed dog (dwarfism with retinal dysplasia 2—drd2) respectively; both of those mutations were excluded in all affected NID." (PMID 31415586, 2019). "Variants associated with OSD have been identified in COL9A3 in the Labrador Retriever and in COL9A2 in the Samoyed dog, termed drd1 and drd2 (dwarfism with retinal dysplasia 1 and 2) respectively." (PMID 31415586, 2019).
muscular atrophy (1 paper, 2009). The loss of muscle tissue due to inactivity or disease. "Muscular atrophy has not been reported earlier in cases with COL9A2 mutations." (PMID 19995321, 2009).
osteochondropathy (1 paper, 2015). "Extensive studies have provided evidence for the associations between the genes COL9A2, COL9A3 and osteochondropathy." (PMID 25774918, 2015).
Parkinson disease (1 paper, 2020). A progressive degenerative disorder of the central nervous system characterized by loss of dopamine producing neurons in the substantia nigra and the presence of Lewy bodies in the substantia nigra and locus coeruleus. "We evaluated the recent literature on candidate blood biomarkers in Parkinson’s disease patients and observed five differentially methylated genes (COL9A2, SCNN1A, AMICA1, SLC16A3, and DLK1) in these studies within our conserved human regions." (PMID 32178731, 2020).
prostate tumor (1 paper, 2021). "Differential expression of COL9A2 in prostate tumor was reported as compared in normal tissues." (PMID 33450964, 2021).
retinal degeneration (1 paper, 2020). Degeneration of the retina. "Defects in both EDN2 and COL9A2 have been previously associated with retinal degeneration." (PMID 32150541, 2020). "Defects in both EDN2 and COL9A2 have been associated with retinal degeneration." (PMID 32150541, 2020).
retinal detachment (1 paper, 2021). An eye emergency condition which may lead to blindness if left untreated. "In the candidate gene approach, COL9A2, COL9A3, NHEJ1, RS1 and NDP genes were investigated based on their known associations with RD and retinal detachment in dogs and humans." (PMID 33945575, 2021).
tumor (7 papers, 2016 to 2025). "Upregulated genes included cartilage-associated genes (COMP, MATN3, and COL11A2), collagen- and extracellular matrix-associated genes (COL9A2, SFRP2, and SERPINE2), and tumor metastasis- and progression-associated genes (SLC38A3, FST, ITGA11, and DGKI)." (PMID 36192442, 2022). "Our data show that expression of EWSR1-FLI1 is associated with the strong production of collagens col1a1b, col1a2, col2a1a, col9a1b, col9a2, and col28a2a both in embryos and in advanced tumors (data not shown), suggesting the importance of specific matrix for tumor development." (PMID 35285802, 2022). "However, the function of the COL9A2 in tumor progression has remained elusive." (PMID 36596829, 2023). "Similarly, two differentially expressed collagen genes (COL9A2 and COL16A1) exhibited negative fold-changes in transcript counts for the grade 3 tumor sample." (PMID 41366031, 2025).
cancer (4 papers, 2012 to 2025). A tumor composed of atypical neoplastic, often pleomorphic cells that invade other tissues. "The upregulated genes were associated with extracellular matrix remodeling and cancer pathways, including LAMC1-3, COL9A2, COL1A1, MYL9, MYH11, and KAT2A." (PMID 39735192, 2024).
connective tissue disorder (4 papers, 2015 to 2025). A disease involving the connective tissue. "These children might be the carrier to the connective tissue disorder due to defective extracellular matrix as seen with COMP, COL2A1, COL9A1, COL9A2, etc. genetic mutation." (PMID 33870477, 2022).
myopathy (4 papers, 2010 to 2025). A disease of the muscle in which the muscle fibers do not function properly. "Most recently COL9A2 exon-skipping mutations in unrelated families have also been linked to mild myopathy, thereby expanding the spectrum of mutant genes involved in MED-associated muscle diseases." (PMID 41155349, 2025). "The results of the present study show that mutations in COL9A2 can also cause myopathy and suggests an important role for type IX collagen in the musculoskeletal system." (PMID 20358595, 2010). "MED-related myopathy has been reported in some families with COL9A3, COMP, and COL9A2 mutations." (PMID 25381065, 2014). "Furthermore, like COL9A3 mutations, myopathy is not a consistent feature of MED caused by COL9A2 mutations." (PMID 20358595, 2010).
Mendelian diseases (1 paper, 2014). "In addition to FANCM, we further evaluated evidence for two other genes COL9A2 and DPYD that were previously implicated in other Mendelian diseases." (PMID 25078778, 2014).
COL9A2 also shares sentences with these, for which no sentence is quoted: myopia (2 papers); vitreoretinal degeneration (2); autoimmune disease (1); autosomal dominant Emery-Dreifuss muscular dystrophy 5 (1); congenital stationary night blindness (1); corneal dystrophy (1); gestational diabetes (1); Human papillomavirus infection (1); hyperopia (1); hypoparathyroidism (1); infection (1); ischemia (1); Kniest dysplasia (1); Marfan syndrome (1); Marshal syndrome (1); melanoma (1); neurodegenerative disease (1); ovarian carcinoma (1); pulmonary fibrosis (1); renal dysplasia (1); reproductive system diseases (1); retinal dystrophies (1); sensorineural hearing loss (1); Stroke (1); Ullrich congenital muscular dystrophy (1); Usher syndrome (1).